SPRED2 (sprouty related EVH1 domain containing 2)
Diseases named in the same sentence as SPRED2 in open-access papers (continued):
Sharing a sentence is not in itself a finding about the gene and the disease.
bladder urothelial carcinoma (1 paper, 2021). "Spred2 gene mutations can be frequently seen in bladder urothelial carcinoma." (PMID 34818323, 2021). "Of note, Spred2 mRNA expression in infiltrating bladder urothelial carcinoma was lower than that in superficial bladder cancer in all three datasets (middle and right)." (PMID 34818323, 2021). "The decreased Spred2 mRNA expression in infiltrating bladder urothelial carcinoma may have affected cancer survival." (PMID 34818323, 2021).
carcinoma in situ (1 paper, 2021). "In situ hybridization demonstrated that Spred2 mRNA was highly expressed in high-grade non-invasive papillary urothelial carcinoma (HGPUC), and the expression was decreased in carcinoma in situ (CIS) and infiltrating urothelial carcinoma (IUC)." (PMID 34818323, 2021).
cognitive deficits (1 paper, 2021). "Furthermore, dysfunction of SPRED1, a homologous member of the SPRED protein family, causes cognitive deficits both in humans and mice, altogether possible reasons for the impaired communication in SPRED2-KOs." (PMID 34679429, 2021).
colon cancer (1 paper, 2016). "To analyze the role of Spred2 expressed in colonic epithelial cells, we knocked down Spred2 expression in the human Caco-2 colon cancer cell line using siRNA and evaluated its effects in vitro." (PMID 27869219, 2016).
fatty liver disease (1 paper, 2019). A reversible condition wherein large vacuoles of triglyceride fat accumulate in liver cells via the process of steatosis. "In the present study, we demonstrate, for the first time, that Spred2 plays an important role in regulating the development of diet-induced obesity, obesity-induced adipose tissue inflammation, and metabolic abnormalities, including fatty liver disease." (PMID 30723473, 2019).
hyperlipidemia (1 paper, 2019). "We demonstrated in this study that the Spred2 KO mice exhibited an exacerbated level of adipocyte hypertrophy and hyperlipidemia (elevated levels of cholesterol, triglyceride, and FFA), suggesting that Spred2 negatively regulates adipocyte hypertrophy and hyperlipidemia." (PMID 30723473, 2019).
infiltrating bladder urothelial carcinoma (1 paper, 2021). An invasive transitional cell carcinoma that arises from the urinary bladder urothelium. "Consistently, database analyses showed that Spred2 expression in infiltrating bladder urothelial carcinoma (invasive) was lower than that in superficial bladder cancer (non-invasive)." (PMID 34818323, 2021).
liver cancer (1 paper, 2024). An epithelial or non-epithelial malignant neoplasm that arises from the liver. "The Cancer Genome Atlas (TCGA) Liver Cancer Database showed a negative association between the level of SPRED2 and p62, a ubiquitin-binding scaffold protein that accumulates when autophagy is inhibited." (PMID 38892460, 2024).
liver fibrosis (1 paper, 2019). "Previous studies have revealed that HFD-fed mice developed liver fibrosis after 9.5 months or 1 year, suggesting a possibility that Spred2 KO mice may develop NASH with liver fibrosis after being fed for a long period of HFD." (PMID 30723473, 2019). "Spred2 deficiency resulted in fatty liver hepatitis without liver fibrosis." (PMID 30723473, 2019).
metabolic syndrome (1 paper, 2019). A cluster of metabolic risk factors for CARDIOVASCULAR DISEASES and TYPE 2 DIABETES MELLITUS. "Spred2 may act as a novel therapeutic tool to treat the progression of pathophysiology associated with metabolic syndrome." (PMID 30723473, 2019). "Thus, over-nutrition caused by HFD exacerbated dyslipidemia in Spred2 KO mice." (PMID 30723473, 2019). "Spred2 knockout (KO) mice, fed with HFD, exhibited an augmented body weight gain, which was associated with enhanced adipocyte hypertrophy in mesenteric white adipose tissue (mWAT) and deteriorated dyslipidemia, compared with wild-type (WT) controls." (PMID 30723473, 2019). "Although Spred2 KO mice have increased fat mass under SD treatment, there was no apparent adipose tissue inflammation and dyslipidemia (data not shown)." (PMID 30723473, 2019).
Obesity (1 paper, 2019). Accumulation of substantial excess body fat. "Thus, for the first time, we identified Spred2 as an important molecule that regulates obesity and obesity-associated metabolic abnormalities." (PMID 30723473, 2019). "Since HFD leads to obesity, particularly in C57BL/6J background, we next fed WT and Spred2 KO mice with HFD and examined their weights." (PMID 30723473, 2019).
sarcoma (1 paper, 2024). A usually aggressive malignant neoplasm of the soft tissue or bone. "SPRED2 inhibits the activation of MAPK/ERK by interacting with rat sarcoma (RAS), ribosomal S6 kinase (RSK) 1, neurofibromin, and RSK2." (PMID 38892460, 2024).
schizophrenia (1 paper, 2017). A major psychotic disorder characterized by abnormalities in the perception or expression of reality. "These include: VAT‐1, DAD‐1, PAQR9, BCKD, BDH, Prickle4, PP2A, RPL13A, SPRED2, KLP, FAM36A, NAB1, CLSTN3, PEDF‐R, and FZD3 (Frizzled gene previously associated with different psychopathologies, most notably Schizophrenia)." (PMID 27696737, 2017).
Sepsis (1 paper, 2017). Sepsis is defined as life-threatening organ dysfunction caused by a dysregulated host response to infection. "Here, we examined whether the absence of Sprouty-related EVH1-domain-containing protein 2 (Spred2), a negative regulator of the Ras/Raf/ERK/MAPK pathway, influences host defense against polymicrobial sepsis (PMS) induced by cecal ligation and puncture (CLP)." (PMID 28993690, 2017).
septic peritonitis (1 paper, 2017). Septic peritonitis is an inflammatory condition of the peritoneum that occurs secondary to microbial contamination. "Since cytokine and chemokine responses are essential in the development of innate immunity against bacterial infections, including septic peritonitis, we hypothesized that Spred2-deficiency might protect mice from septic peritonitis." (PMID 28993690, 2017). "To test the hypothesis that interfering Spred2 protects mice from PMS, we first induced septic peritonitis in WT and Spred2−/− mice by CLP and examined the survival of mice." (PMID 28993690, 2017).
steatosis (1 paper, 2019). Increased lipid within the cytoplasm of cells. "Histologically, in comparison with WT-livers, Spred2 KO-livers revealed moderate vesicular steatosis, and influx of neutrophils and F4/80-positive macrophages." (PMID 30723473, 2019).
Stroke (1 paper, 2023). Sudden impairment of blood flow to a part of the brain due to occlusion or rupture of an artery to the brain. "SPRED2 affects neurological recovery after stroke by reducing cell migration through the ERK/c-Fos/MMPs pathway." (PMID 36720935, 2023).
Type 1 Diabetes (1 paper, 2024). "We found GWAS links between 7 T2D-DMP genes and T2D or related phenotypes, including SPRED2 (T2D), ITPR1 and PLD6 (Diabetic complications), SLC16A3 (BMI), TCF7 (Type 1 Diabetes), RGL3 (blood pressure) and TNIP1 (autoimmune traits)." (PMID 38574408, 2024).
tumor (27 papers, 2013 to 2025). "For example, several genes linked to RA credible SNPs in FLS were implicated in cell proliferation and tumor development (e.g., SPRED2, GRHL2, CDK6, RUNX1, and ZFP36L)." (PMID 34433485, 2021). "This notion was further supported by our observation that Spred2-mediated tumor cell death was impaired by either mutations in the LIR motifs in Spred2 or knockdown of ATG5, LC3 or p62." (PMID 27028858, 2016). "Taken together, our study provides new insights into the underlying mechanisms by which Spred2 induces tumor cell death." (PMID 27028858, 2016). "In this study, we show that Spred2 induces autophagy-associated tumor cell death by increasing autophagosome maturation." (PMID 27028858, 2016). "SPRED2 protein levels are strongly inversely associated with tumor progression and metastasis." (PMID 35205702, 2022). "Given that autophagy plays a role in cell death triggered by tumor suppressors, we hypothesized that Spred2 induces autophagy-associated cell death." (PMID 27028858, 2016). "Importantly, both the functional LIR and Spred2-associated autophagy are required for Spred2 to induce tumor cell death." (PMID 27028858, 2016). "In the present study, we show that Spred2-associated autophagy can induce tumor cell death." (PMID 27028858, 2016). "Increased miR-210 and reduced SPRED2 levels were found in aorta of mice under high-fat diet and tumor tissues, which implied that miR-210 can be an underlying mechanism to explain oxLDL as a common risk factor for cardiovascular disease and gastrointestinal cancer." (PMID 26254226, 2015). "We previously demonstrated that SPRED2 is localized in the cytoplasm of non-tumor cells and that the presence of SPRED2 on cell membrane suppresses the progression of noninvasive papillary urothelial carcinoma, likely by inhibiting the RAS/RAF/ERK pathway." (PMID 41155378, 2025). "We recently showed that downregulation of SPRED2 in HCC promotes tumor cell proliferation, EMT, stemness, and anti-apoptotic properties, and leads to more malignant phenotypes through increased activation of MAPK/ERK." (PMID 38892460, 2024). "In our study, we found that SPRED2 can act as a tumor suppressor in BC as well, and that decreased levels of SPRED2 can increase their cell proliferation and migration capacity." (PMID 35205702, 2022). "The METTL3 deficient mice decreases m6A methylation level of SPRED2, which can’t be recognized by YTHDF1, thus the reduction of SPRED2 translation leads to enhance NF-κB activation and promote tumor progression." (PMID 35022030, 2022). "We first examined Spred2 mRNA expression in various categories of 85 urothelial lesions including non-tumor, PUNLMP, LGPUC, HGPUC, CIS, and IUC." (PMID 34818323, 2021). "m6A sequencing reveals that loss of METTL3 impairs the YTHDF1-mediated translation of SPRED2, which enhances the activation of NF-kB and STAT3 through the ERK pathway, leading to increased tumour growth and metastasis." (PMID 33654093, 2021). "This increases the expression of miRNA-1246, associated with metastasis, resulting in the downregulation of the expression of the anti-oncogene SPRED2 and leading to tumour metastasis." (PMID 34246319, 2021). "The METTL3/miR-1246/SPRED2 axis plays an important role in tumour metastasis as abnormal m6A modification of in CRC leads to the upregulation of METTL3 expression, and pri-miR-1246 can be further processed." (PMID 34246319, 2021). "In all non-tumor cases, Spred2 was positive in cytoplasm of basal and lower intermediate cells (pattern C+M-, 101/101 cases)." (PMID 34818323, 2021). "We decided to study the SPRED2 tumor suppressor to discover its role with regard to MAPK inhibition." (PMID 38831555, 2020). "The present study demonstrates that the METTL3/miR-1246/SPRED2 axis plays an important role in tumor metastasis and provides a new m6A modification pattern in CRC development." (PMID 31492150, 2019).
tumor (continued). "SPRED2 was chosen for further research for its anti-oncogene role in tumorigenesis, and low expression of SPRED2 was noted in tumor tissue than in the adjacent normal tissues in both TCGA and our patient tissues." (PMID 31492150, 2019). "Together, our data uncover a novel mechanism by which Spred2 exhibits its tumor suppressor function." (PMID 27028858, 2016). "Our results demonstrated that Spred2, a tumor suppressor, enhances the autophagic process in cancer cells by increasing autophagosome maturation." (PMID 27028858, 2016). "Together, these data indicate that inhibition of autophagy attenuates Spred2-mediated cell death in tumor cells." (PMID 27028858, 2016). "Collectively, these data indicate that Spred2 induces tumor cell death in an autophagy-dependent manner." (PMID 27028858, 2016). "Collectively, our results indicate that Spred2 triggers tumor cell death in an autophagy-dependent manner." (PMID 27028858, 2016). "Silencing the expression of autophagy-related genes ATG5, LC3 or p62 in HeLa and A549 cells gave similar results, suggesting that autophagy is required for Spred2-induced tumor cell death." (PMID 27028858, 2016). "Taken together, this study demonstrates that through its interaction with LC3, Spred2 enhances autophagosome maturation thereby contributing to tumor cell death." (PMID 27028858, 2016). "We previously reported that tyrosines 303/343/353 at the SPR domain is essential for Spred2-mediated inhibition of tumor cell growth." (PMID 27028858, 2016). "Previous studies have primarily examined the independent tumor-suppressive functions of NF1 or SPRED2 in various cancers; however, the cooperative interaction between these proteins and their biological significance in BC remain unclear." (PMID 41155378, 2025). "The expression levels of SPRED1 and SPRED2 in tumor tissues are lower than those in normal tissues, suggesting that the downregulation of SPRED1 and SPRED2 may serve as important indicators of tumor initiation and progression." (PMID 38402263, 2024). "Strikingly, ablation of METTL3 in myeloid cells promoted tumor growth and metastasis, associated with decreased YTHDF1-mediated translation of SPRED2 and increased activation of NF-kB and STAT3 through the ERK pathway, leading to increased tumor growth and metastasis." (PMID 37369946, 2023). "Therefore, our results support the role of SPRED2 as a tumor suppressor and indicate that it is important in modulating cell proliferation and the migration of ERα+ BC cells." (PMID 35205702, 2022). "These previous findings suggested that Spred2 function as a potential tumor suppressor gene." (PMID 34818323, 2021). "Subcellular immunolocalization of Spred2 in each tumor category." (PMID 34818323, 2021). "And METTL3/miR-1246/SPRED2 axis played an important role in tumor metastasis." (PMID 31492150, 2019). "Spred2 functions as a tumor suppressor in a variety of cancers." (PMID 27028858, 2016). "We demonstrate that Spred2 induces autophagy and enhances autophagosome maturation in tumor cells." (PMID 27028858, 2016). "Our study also suggests that autophagy may be a potential target for enhancing Spred2-mediated anti-tumor activity." (PMID 27028858, 2016). "Conversely, knockdown of Spred2 in tumor cells inhibited upregulation of autophagosome maturation induced by the autophagy inducer Rapamycin, which could be reversed by the rescue Spred2." (PMID 27028858, 2016). "In addition, Spred2 interacts and co-localizes with p62 and depletion of p62 in tumor cells, attenuating Spred2-triggered cell death." (PMID 27028858, 2016). "Mechanistically, Spred2 interacts and co-localizes with LC3 via the LIR motifs in the SPR domain, while the functional LIR motifs mediate Spred2-associated autophagosome maturation and contribute to Spred2-induced tumor cell death." (PMID 27028858, 2016). "To test this, we first examined whether Spred2 induces autophagy in tumor cells." (PMID 27028858, 2016).
tumor (continued). "LC3-II levels were significantly lower in SPRED2-KO tumors as compared to control tumors, and tumor p62 and TOM20 levels were significantly higher in SPRED2-KO tumors compared to control tumors." (PMID 38892460, 2024). "Down-regulating SPRED2 further reverses the inhibition of MAPK pathway and promotes the invasion and metastasis of tumor cells." (PMID 35022030, 2022). "Mutations in the LIR motifs or deletion of the SPR domain impaired Spred2-mediated autophagosome maturation and tumor cell death, indicating that functional LIR is required for Spred2 to trigger tumor cell death." (PMID 27028858, 2016). "Similarly, SPRED2 overexpression inhibited proliferation and induced apoptosis, while SPRED2 knockdown increased ERK phosphorylation and accelerated tumor growth in vivo." (PMID 41155983, 2025). "Tumor cells showed lower levels of SPRED2 immunoreactivity compared to adjacent non-tumor cells (left)." (PMID 38892460, 2024). "Sprouty and SPRED proteins are known to be negative regulators of MAPK signaling and may thus function as tumor suppressors, whereas SPRED1 and SPRED2 have been additionally found to be negative regulators of hematopoiesis." (PMID 28882895, 2017). "There was a negative correlation between SPRED2 and p62 in the tumor, but not in the adjacent area." (PMID 38892460, 2024). "Therefore, METTL3 collaborates with YTHDF1 to promote tumor progression and attenuate the efficacy of tumor therapy by targeting the SPRED2/ERK/NF-kB-STAT3 signaling pathway, highlighting the clinical possibilities of using METTL3 as a target in tumor immunotherapy." (PMID 39416774, 2024).